FASN (fatty acid synthase)
Diseases named in the same sentence as FASN in open-access papers (continued):
Sharing a sentence is not in itself a finding about the gene and the disease.
cancer (continued). "Further, a statistically significant relationship was presumed between FASN expression and cancer-associated fibroblasts for CESC, KIRC, KIRP, OV, and UVM; however, a negative correlation was presumed for LGG, PRAD, and STAD." (PMID 34879004, 2021). "More importantly, further investigation is warranted to gain a better understanding of the relationship and dynamics between cancer metabolism, oncogenic mutations and activation of other signaling pathways in FASN-positive tumors." (PMID 32872164, 2020). "FASN has been found overexpressed in nearly all of cancer tissues, and its expression is associated with a poorer prognosis." (PMID 33194695, 2020). "FASN is preferentially overexpressed in cancer cells and has been strongly linked to cancer cell proliferation and migration." (PMID 32676035, 2020). "Treatment with FASN inhibitors is therefore necessarily associated with severe metabolic aberrations in the cancer cells." (PMID 32913236, 2020). "Elevated expression of FASN is found to be associated with poor prognosis and higher risk of recurrence in a number of human cancers." (PMID 32826925, 2020). "Here, we provide evidence that overexpression of the HER3 ligand HRG suffices to up-regulate the expression of cancer-associated FASN independently of HER2 overexpression." (PMID 33081219, 2020). "Cancer cells have been described to increase the de novo lipogenesis through the activation of FASN and its inhibition has proven to cause cell death." (PMID 32438613, 2020). "One of the features of cancer cells is the increased de novo lipogenesis, and FASN is part of the metabolic reprogramming cancer hallmark." (PMID 32695216, 2020). "Based on our data, FASN would be a necessary checkpoint for the acquisition of this essential hallmark of cancer." (PMID 31676791, 2019). "Under these conditions, expression of fatty acid synthase (FASN), known to be associated with cancer aggressiveness, was strongly reduced in the xenograft tumors." (PMID 30241339, 2018). "Recent studies have linked FASN overexpression in cancer with multidrug resistance, which partially explains the association between FASN expression and poor prognosis." (PMID 29569717, 2018). "It has been shown that leptin and resistin stimulate the Akt signaling in cancer cells, and hyperactivated Akt pathway was associated with increased protein levels of FASN and Cav-1." (PMID 29568521, 2018). "We demonstrated that CRC PDXs and CRC cells show a wide range of sensitivity to FASN inhibition and that high levels of FASN expression are associated with increased sensitivity of cancer cells to TVB inhibitors in vitro." (PMID 29872506, 2018). "In attempt to correlate the response of FASN inhibition to the mutational profile of tumors, we assessed the mutational status of 198 cancer-related genes." (PMID 29872506, 2018). "FASN is frequently upregulated in various cancers, and its increased expression is associated with chemoresistance, metastasis, and poor prognosis." (PMID 30445800, 2018). "Fatty acid synthase (FASN) is the only enzyme engaged in long-chain saturated fatty acid synthesis and is implicated in cancer progression by regulating lipid raft function." (PMID 29301373, 2018). "FASN is crucial for cancer cell survival, and its overexpression has been associated with poor prognosis, higher risk of cancer recurrence, and drug resistance, in colon and ovarian cancer, breast and renal cell carcinomas." (PMID 29449326, 2018). "The tumor-associated expression of FASN and its pro-tumorigenic functions characterized in multiple studies make this enzyme an attractive target for anti-cancer therapy." (PMID 29872506, 2018). "High expression of FASN is associated with the development and survival of tumor cells, as well as a poor cancer prognosis." (PMID 29805774, 2018). "In summary, these data further suggest that anti-cancer effect of FASN inhibition is associated with a significant impact on lipid composition." (PMID 29872506, 2018).
cancer (continued). "In most of the cancers, cause of increased lipogenesis is due to overproduction of enzyme, fatty acid synthase (FASN)." (PMID 28373964, 2017). "Aberrant FASN function is associated with tumourigenesis in various human cancers, making it a potential cancer drug target." (PMID 27852311, 2016). "The ability of flavonoids to induce apoptosis in cancer cells is strongly associated with their capability to inhibit FASN." (PMID 27602772, 2016). "Increase in the level of FASN and Cav-1 has been reported to be associated with development of resistance to cancer therapy." (PMID 27980732, 2016). "Overexpression of FASN has been strongly associated with many cancer types and is under extensive study as a potential cancer drug target." (PMID 27270654, 2016). "High expression of FASN also associates with poor prognosis and inhibition of FASN results in cancer cell death and reduction in tumor volume." (PMID 26934656, 2016). "Overexpression of FASN has been strongly associated with many cancer types because it plays important metabolic roles in molecular pathways regulating cancer cell proliferation and tumor development." (PMID 27072583, 2016). "A lipogenic enzyme, FASN, is important for drug resistance in various cancers, although the underlying mechanism remains obscure." (PMID 27589734, 2016). "Clinically, immunohistological evaluation of surgical specimens showed that high FASN expression was significantly associated with a high GS and an advanced pT stage of cancer." (PMID 26878389, 2016). "A growing body of evidence indicates that FASN, the only enzyme that synthesizes fatty acids, acts as an oncogene and its overexpression is associated with poor prognosis in several malignant tumors." (PMID 25669981, 2015). "In fact, increased risk of cancer has been linked to both dietary fat intake and increased intracellular levels of palmitate synthesized de novo by fatty acid synthase." (PMID 26275289, 2015). "Blocking FASN activity causes in vitro and in vivo anticancer activity in several overexpressing FASN human carcinomas." (PMID 26107737, 2015). "The finding that palmitic acid rescued quercetin-induced apoptosis in cancer cells confirmed that the induction of apoptosis was associated with the inhibition of FASN." (PMID 25009654, 2014). "Elevated expression of FASN has been linked to poor prognosis and reduced disease-free survival in numerous types of cancer." (PMID 25009654, 2014). "Although the ultimate mechanism of cancer-associated FASN overexpression is not completely understood, it has been shown that FASN inhibitors such as C75 and orlistat are promising potential anticancer drugs." (PMID 25009654, 2014). "An increased FASN expression is associated with the cancer progression, higher risk of recurrence and shorter survival in many types of cancers." (PMID 23725225, 2013). "Fatty acid synthase (FASN) expression is elevated in several cancers, and this over-expression is associated with poor prognosis." (PMID 23741342, 2013). "Intriguingly, recent experimental evidence supports the notion that the oncogenic nature of FASN-associated lipogenesis closely depends on the activity and expression of key cancer-related oncogenes such as HER2." (PMID 23725225, 2013). "Though there are many potential causes for its upregulation, the transcriptional regulation of FASN expression has been considered to be the major cause for the increased FASN expression in cancer cells." (PMID 23725225, 2013). "The overexpression of FASN is observed in several types of human cancer and this overexpression is reportedly associated with poor prognosis." (PMID 23741342, 2013). "Rapidly-proliferating cancer cells often have a robust program of fatty acid synthesis accompanied by high-level expression of associated genes such as fatty-acid synthase." (PMID 22457791, 2012).
cancer (continued). "The use of FASN inhibition as anticancer therapy was first described with Cerulenin (a natural antibiotic from Cephalosporium ceruleans) that causes apoptotic cancer cell death in vitro." (PMID 22769244, 2012). "MT19c targets the cancer cell metabolism machinery, specifically FASN functions and abrogates de novo lipogenesis, the hallmark of cancer cells." (PMID 22509304, 2012). "The up-regulation of FASN expression in numerous types of cancer and its association with poor outcome have long suggested its role in human malignancy." (PMID 19517019, 2009). "As a result of an increase in lipogenesis and the changes in cell death susceptibility, FASN might limit the uptake of chemotherapeutics such as doxorubicin and make cancer cells less susceptible to cytotoxic agents." (PMID 40133809, 2025). "In addition to its role in fatty acid synthesis, abnormal expression of FASN is implicated in various diseases, such as metabolic disorders, cancers, and inflammatory diseases." (PMID 41196069, 2025). "Cancer-associated proteins can modulate lipid metabolism by activating crucial enzymes such as fatty acid synthase (FASN) and acetyl-CoA carboxylase (ACC), which are vital for de novo lipogenesis, promoting lipid accumulation and supplying energy for tumor growth." (PMID 40641601, 2025). "Similar to key mutations in oncoproteins (G12 in KRAS, V600 in BRAF, or T41 in β-catenin), we investigated whether mutations at T980 occur in FASN across various cancers." (PMID 40684943, 2025). "FASN has been identified in EVs associated with breast and prostate cancers." (PMID 40214422, 2025). "Thus, by causing ferroptosis, targeting FASN appears to be a viable tactic to stop the spread of cancer." (PMID 40901481, 2025). "Moreover, the abnormal expression of FASN has been proved to be associated with the sensitivity and prognosis of malignant tumors to immunotherapy, especially PD-1 therapy." (PMID 38272906, 2024). "The overexpression and enhanced activity of FASN, a crucial metabolic multi-enzyme in modulating the terminal catalytic step in FA synthesis, leads to alterations in the phenotype of cancer cells and is often associated with a high risk of disease recurrence and death." (PMID 39332525, 2024). "Taken together, these results suggest that suppression of FASN increases the susceptibility of cancer cells to CAT killing through a mechanism that may involve alterations in mitochondrial priming." (PMID 39349429, 2024). "However, it is noteworthy that our mathematical deconvolution revealed that FASN loss-induced sensitization to the cytotoxic activity of CATs paralleled a FASN loss-induced reduction in the carrying capacity of cancer cell populations." (PMID 39349429, 2024). "Additionally, a deeper exploration of the mechanisms underlying the increased vulnerability of FASN in CSCs compared to normal cancer cells is essential for the development of more effective therapeutic strategies." (PMID 38994204, 2024). "Fatty acid synthase (FASN)-catalyzed endogenous lipogenesis is a hallmark of cancer metabolism." (PMID 39349429, 2024). "FASN, the sole cytosolic enzyme responsible for de novo palmitate synthesis in mammalian cells, has been associated with poor prognosis in cancer and shown to cause drug and radiation resistance by upregulating DNA damage repair via suppression of p65 expression." (PMID 38467328, 2024). "Targeting FASN may represent a novel strategy to circumvent cancer immune resistance that warrants clinical exploration to improve cancer susceptibility to T cell-based immunotherapies and immunotherapy in general." (PMID 39349429, 2024). "Similarly, FASN-mediated major histocompatibility complex class II (MHC-II) suppression is a potentially widespread mechanism underlying the cancer cell escape from early immune detection." (PMID 39349429, 2024).
cancer (continued). "Here, we speculated that cancer cells are pushed closer to apoptotic thresholds upon FASN loss (primed), thereby allowing less powerful hits or less frequent T-cell punches due to low E:T becoming sufficient to enable T-cell mediated destruction." (PMID 39349429, 2024). "We took advantage of cancer cells engineered to carry a loss-of-function in FASN as a unique opportunity to investigate whether cancer cells may adapt to the loss of de novo FA biosynthesis when fighting T-cell attack." (PMID 39349429, 2024). "Thus, across cancer types, high FASN expression is often associated with tissue, cellular, and molecular features of immune evasion." (PMID 39349429, 2024). "A range of FASN inhibitors have now been implicated for cancer therapy." (PMID 38610991, 2024). "Moreover, FASN overexpression and hyperactivity commonly occurs in carcinomas with higher risk of both disease recurrence and death." (PMID 38402237, 2024). "The, at least partial, link between differentially altered FASN expression and its promoter methylation also suggests an underlying crosstalk between genome and epigenome in the deregulation of FASN in cancer, which often seems unrelated to mutational processes." (PMID 36650542, 2023). "Moreover, elevated FASN expression was observed in several other cancer types and associated with a poor prognosis of patients." (PMID 37696831, 2023). "FASN is a lipogenic enzyme that is considered as a metabolic reprogramming cancer hallmark." (PMID 37587470, 2023). "The incidence of mutations in FASN was also low in both cancer types." (PMID 36650542, 2023). "Thus, we performed a pan-cancer analysis to evaluate the association between FASN expression and immune infiltration in TCGA datasets." (PMID 37696831, 2023). "In cancer cell lines, FASN over-expression was found to cause chemotherapy resistance induced by drug-containing media, suggesting that FASN may be a causing factor of cancer chemoresistance." (PMID 38003694, 2023). "Activation of FASN increased de novo fatty acid (FA) synthesis, a hallmark of cancer cells." (PMID 37620304, 2023). "FASN enzyme is involved in the endogenous synthesis of PA and its overexpression has been linked to poor prognosis, recurrence, and aggressiveness in a variety of cancers." (PMID 36816174, 2022). "Treatment with the FASN blocker orlistat caused antiangiogenic effects already at lower doses than that needed to impair cancer cell growth, offering a therapeutic window to use FASN inhibitors as an alternative antiangiogenic agent in cancer patients." (PMID 36232355, 2022). "Higher FASN expression was observed to be linked to higher pathological stages and poorer patient prognosis in breast, ovarian, cervical and endometrial cancers." (PMID 35448537, 2022). "In addition, we examined the FASN mutation status in all types of cancer and found that FASN showed a higher gene mutation frequency in SKCM (13.52%), UCEC (13.24%), and LIHC (10.49%)." (PMID 36555243, 2022). "Consequently, high expression of FASN is a feature of many cancers, including colon, prostate, and breast cancers, and is associated with poor prognosis and disease-free survival." (PMID 34983949, 2022). "However, activation of FASN is a hallmark of cancer contributing to tumor growth, invasion and stemness." (PMID 35646898, 2022). "FASN expression is associated with the prognosis of patients with malignant tumors." (PMID 35566090, 2022). "Findings gleaned from our study suggest that FASN mutation-mediated FA metabolism may be considered as an indicator for cancer immunotherapy efficacy evaluation." (PMID 36428733, 2022).
cancer (continued). "In addition, FASN gets involved in the regulation of cancer-associated metabolic reprogramming, and targeting FASN has been regarded as an effective method in treating BC." (PMID 35070947, 2021). "For instance, acetyl-CoA carboxylase alpha (ACACA) overexpression associates with increased cancer risk and can be detected in early-stage BC, while fatty acid synthase (FASN) promoted BC metastasis and was proposed as a potential therapeutic target for BC treatment." (PMID 34572770, 2021). "The underlying mechanisms may be the cancer proliferation caused by glucose uptake and fatty acid synthase." (PMID 33763366, 2021). "Furthermore, studies showed that the overexpression of FASN is associated with cancer cell proliferation, metastasis, poor prognosis and a high risk of recurrence." (PMID 34421595, 2021). "Additionally, overexpression of FASN was also associated with cancer progression and poor prognosis in colorectal, breast, and prostate cancers." (PMID 32276528, 2020). "Identifying susceptible cancer cell populations resistant to FASN inhibitors is therefore critical." (PMID 32872164, 2020). "Furthermore, the elevated mitochondrial respiration and fatty acid oxidation link a positive association between FASN and the high energy demand metastatic cancer cells." (PMID 32872164, 2020). "Therefore, it is logical to infer that overexpression of FASN is associated with increased protein palmitoylation, which then contributes to worse prognoses in certain cancers." (PMID 32792852, 2020). "Indeed, it has been shown that FASN is frequently up-regulated in various cancers, and its increased expression is associated with chemoresistance, metastasis, and poor prognosis." (PMID 31717414, 2019). "In normal cells, the main function of FASN is long-chain fatty acid synthesis; however, transforming cells can harness this enzymatic reaction to support transformation by eliciting the acquisition of a hallmark of cancer, 3D anchorage-independent growth." (PMID 31676791, 2019). "For example, acetyl-CoA serves as a critical precursor substrate for the de novo synthesis of fatty acids mediated by cytosolic fatty acid synthase (FASN), known to be a central factor underlying the survival, uncontrolled proliferation and progression of numerous types of cancer cells." (PMID 30992471, 2019). "Loss of FASN can reduce the energy metabolism, proliferation, and migration of cancer cells." (PMID 30237984, 2018). "Fatty acid synthase (FASN) has been linked with several types of cancer." (PMID 29112149, 2017). "For example, over-expression of the receptor tyrosine kinase (RTK), human epidermal growth factor 2 (HER-2) by gene amplification, is linked to an aggressive cancer cell subtype by inducing up-regulation of a key lipogenic enzyme, the fatty acid synthase (FASN)." (PMID 29257069, 2017). "Furthermore, the association between FASN and proliferation and its role in tumor growth suppression due to its inhibition has already been observed both in vivo and in vitro in several carcinomas." (PMID 29088795, 2017). "Interestingly, overexpression of FASN has also been strongly associated with many biologically aggressive cancer types and is under extensive study as a potential cancer drug target." (PMID 27270654, 2016). "However, earlier studies indeed revealed that cancer cell-associated FASN can actively regulate tumor vasculature through altering the profile of secreted angiogenic factors including VEGF165, and regulation of their bioavailability." (PMID 27713913, 2016). "FASN expression is drastically increased under pathological conditions, and it has been associated with the development of a variety of diseases including cardiovascular disease, insulin resistance of type 2 diabetes and many types of cancers." (PMID 26808816, 2016). "Further, increased FASN expression in malignant tumors is associated with a poor prognosis." (PMID 24964211, 2014).